RUNX3 (RUNX family transcription factor 3)
Diseases named in the same sentence as RUNX3 in open-access papers (continued):
Sharing a sentence is not in itself a finding about the gene and the disease.
cancer (continued). "Ubiquitination and proteasomal degradation represent a major mechanism for the inactivation of RUNX3 and the suppression of cancer cell proliferation." (PMID 36899853, 2023). "RUNX3 has been reported to control cellular senescence, a potent anti-cancer mechanism that prevents the proliferation of potentially cancerous cells." (PMID 37759525, 2023). "RUNX3 has since been shown to be inactivated by genetic/epigenetic changes or protein mislocalization in various human cancers, including gastric, colorectal, lung, pancreatic, breast, liver, and prostate cancers, as well as leukemia and neuroblastoma." (PMID 37190031, 2023). "First, we examine the role of RUNX3 in mediating the ubiquitination and proteasomal degradation of oncogenic proteins in cancer." (PMID 36899853, 2023). "RUNXs belong to a family of metazoan transcription factors, and there are three main RUNX in mammals (namely, RUNX1, RUNX2, and RUNX3), which are the major regulators of development and often deregulated in human cancers." (PMID 36321611, 2023). "RUNX3 is frequently inactivated in human cancers by promoter DNA hypermethylation, histone modification, hemizygous deletion, and protein mislocalisation." (PMID 37759525, 2023). "In the present study, we first performed a pan-cancer analysis of the expression of RUNXs and then demonstrated that RUNX1, RUNX2, and RUNX3 are highly expressed in various cancers." (PMID 36321611, 2023). "Further studies of RUNX3R122C/R122C mice will provide insights on the function of RUNX3 on the intrinsic self-renewal capacity of stem cells, as well as their communication with the immune environment during cancer initiation." (PMID 36766749, 2023). "As a combination treatments are the preferred options for most cancers, a combination of therapeutic drugs with RUNX3 activity is essential to increase therapeutic efficacy." (PMID 37438719, 2023). "The expression of RUNX3 in 12 of 32 cancers was found to be modified relative to that in the corresponding normal tissues, which included increased expression in 7 cancers and decreased expression in 5 cancers." (PMID 36321611, 2023). "Next, we examine the cellular mechanisms and pathways that facilitate ubiquitination and proteasomal degradation of RUNX3 in cancer." (PMID 36899853, 2023). "The fact that RUNX3 is frequently hypermethylated in cancer begs the question: will reactivation of the silenced RUNX3 to stem aberrant MYC activity?" (PMID 37400551, 2023).
cancer (continued). "Correlation coefficients between RUNX3 transcript levels and copy number alterations (CNA) or mutation counts were computed for all cancers." (PMID 37190015, 2023). "Because RUNX3 is sometimes functionally inactivated due to cytoplasmic mislocalization in cancer cells, we examined subcellular localization of RUNX3 in exp‐CAF 544 cells." (PMID 37641472, 2023). "The promoter region of RUNX3 gets methylated which leads to an inactivation of RUNX3, reported in several carcinomas." (PMID 37046772, 2023). "RUNX3 plays an anti-angiogenic role through the degradation of HIF-1α under hypoxia or the direct suppression of VEGF gene expression in cancers." (PMID 36231060, 2022). "RUNX3 (located at 1p36, a chromosomal region often deleted in several types of cancer) has a major role in the development of gastro-intestinal tract, neurogenesis and thymopoiesis." (PMID 35075235, 2022). "For the first time, we used TCGA, Oncomine, and cBioPortal to analyze the RUNX gene family (RUNX1, RUNX2, and RUNX3) in 33 distinct human cancer types and matched normal tissues." (PMID 35522574, 2022). "RUNX3 is a transcription factor that can act as a tumour suppressor and repress cancer cell migration and metastasis in HCC." (PMID 35264787, 2022). "In different cancer types, such as lung, bone, bladder, and colon, RUNX3 expression was found to be suppressed by hypermethylation of the promoter region." (PMID 36429115, 2022). "Measurements of the expression of RUNX3 mRNA in these patients indicated a significantly lower level in cancer tissues than in adjacent tissues." (PMID 36518886, 2022). "RUNX3 is silenced by hypoxia both at the gene and protein levels in cancers by hypoxia-induced HDAC1 and/or G9a HMT." (PMID 36231060, 2022). "In this study, we first examined the expression of RUNX3 in cancer tissues and adjacent normal tissues of 30 patients with CCRCC." (PMID 36518886, 2022). "High significance of the runt-related transcription factor family (RUNXs), including RUNX1, RUNX2, and RUNX3, which are involved in developmental processes, immune response, and cancer, was also identified." (PMID 35629968, 2022). "Taken together, these results suggest a novel and critical role for RUNX3 in hypoxic responses such as cancer progression, angiogenesis, stem cell maintenance, and ischemic diseases." (PMID 36231060, 2022). "Qualitative modeling was then performed to unfold the cellular events involved in the epigenetic, that is, DNMT1-mediated silencing of RUNX3 that leads to cancer invasion." (PMID 35898303, 2022). "The results revealed that the onset of oncogene c-myc introduces pathogenesis in the system and its consistent activation along with persistent suppression of TSG RUNX3 hyperactivates DNMT1 leading to cancer metastasis." (PMID 35898303, 2022). "Since aberrant methylation is the main reason of RUNX3 inactivation in cancer, reversal of DNA methylation by demethylating agents should restore RUNX3 activation preventing transcription of Notch target genes." (PMID 33804511, 2021). "This RUNX3–mitotic structure interaction is crucial for on-time mitotic progression, as it was shown in several cancer cell lines." (PMID 34421907, 2021). "Hypermethylation of the RUNX3 promoter, with most of the published data showing significance of distal promoter methylation, is a frequent finding for several cancers." (PMID 34421907, 2021). "Cancer-linked bone obliteration in NSCLC, the upstream receptor of CCL-5, Runt-related Transcription Factor-3 (RUNX3), was rather helpful when expressed a little." (PMID 34336101, 2021).
cancer (continued). "As the use of the DNA methyltransferase (DNMT) inhibitor (5-aza-2′-deoxycytidine) also promoted RUNX3 expression in several cancer cell lines, the role of DNA methylation in RUNX3 regulation cannot be omitted." (PMID 34884658, 2021). "Promoter methylation of the CpG islands of RUNX3 and overexpression of enhancer of zeste homolog 2 (EZH2) has been suggested to downregulate RUNX3 in cancer." (PMID 32943993, 2020). "We have identified a unique role for TrkB in the regulation of BMP and RUNX3-mediated growth inhibition of cancer cells." (PMID 32731498, 2020). "The data presented in this study provide new insights into the biology of RUNX3 and highlights the need to revisit our current understanding of the role of RUNX3 in cancer." (PMID 32943993, 2020). "In the RUNX3→GPR15 case, we adopted dysregulation relationship between RUNX3 and GPR15 to confirm the anti-cancer function of RUNX3 in CRC." (PMID 32717065, 2020). "According to gene dysregulation analysis, the regulatory intensity of RUNX3→GPR15 is decreased from normal to cancer, which suggests that RUNX3 at least partly contributes to the high expression of GPR15 in normal." (PMID 32717065, 2020). "CpG island hypermethylation in promoter region of TGSs as death-associated protein kinase (DAPK), O6-methylguanine DNA methyltransferase (MGMT) and runt-related transcription factor 3 (RUNX3) have been consistently observed in many human cancers." (PMID 32870234, 2020). "The CpG site maps to gene RUNX3, a runt domain-containing transcription factor and a known tumor suppressor, frequently deleted or transcriptionally silenced in cancer according to the NCBI Gene database." (PMID 32583859, 2020). "And we also revealed PIM1 inhibition as a new strategy to target at cancer stem cells population and RUNX3 was essential to the anti‐BrCSC effect of PIM1 inhibition." (PMID 32307917, 2020). "The 10% most abundantly expressed circRNAs were derived from genes demonstrating enrichment in the lysine degradation (p = 0.03), attenuation phase (p = 0.02), RUNX3 (p = 0.02), carcinoma (p = 0.01) and stem cell gene regulation (p < 0.001) pathways." (PMID 32312268, 2020). "RUNX3, as a tumor suppressor gene, is frequently inactivated in human cancer cell lines and patient samples." (PMID 31122259, 2019). "Treatment of the cells with an ROS scavenging chemical, N-acetyl-l-cysteine, severely compromised TRAIL-mediated apoptosis in RUNX3-overexpressing cancer cells." (PMID 31022877, 2019). "The findings of this study are exciting, and future studies must converge on the analysis of the role of RUNX3 in different cancers." (PMID 31022877, 2019). "miR-106b and its target gene Runt-related transcription factor 3 (Runx3) have also been identified as capable of modulating cancer progression." (PMID 31798638, 2019). "Our meta-analysis was unable to find any statistical significance between HBV-positive carcinoma tissues and HBV-negative carcinoma tissues for the methylation of the remaining seven genes, including RUNX3, p14, WIF1, CDH1, PRDM2, SOCS1 and MGMT." (PMID 31772678, 2019). "In these cancers, RUNX3 inhibits oncogenic Wnt signaling by interacting with β-catenin and promotes TGF-β-induced growth inhibition by interacting with SMAD3/SMAD4." (PMID 28030842, 2017). "Since EMT was characterized by cancer cell migration and invasion, we detected the expression level of E-cadherin and Vimentin in cells with control or RUNX3 plasmids or control siRNA or RUNX3 siRNA." (PMID 28977878, 2017). "To estimate the clinical significance of RUNX3 expression, we analyzed The Cancer Genome Atlas (TCGA) microarray data." (PMID 28030842, 2017). "We used qRT-PCR to detect miR-6780a-5p levels in RCC cancer cells 786-O and OS-RC-2 with RUNX3 overexpressed or knocked down." (PMID 29254144, 2017). "The RUNX3 gene resides on human chromosome 1p36, a region that genomic deletion frequently happened in various human cancers, including BC." (PMID 27825140, 2017).
cancer (continued). "When inhibition of RUNX3 expression in RCC cancer cells, immunoprecipitated DNA from the miR-6780a-5p promoter was reduced." (PMID 29254144, 2017). "In summary, RUNX3 participates in cancer-induced bone destruction by affecting the survival, migration, invasion, and/or TGF-β responsiveness of OSCC cells and by increasing the production of PTHrP by OSCC cells." (PMID 28030842, 2017). "Function studies identified that RUNX3 overexpression repressed cell migration and invasion in cancer cells." (PMID 28977878, 2017). "Previous evidences in cell lines, knockout animals, and primary human cancer tissues have indicated that RUNX3 as a suppressor is inactivated in BC by reduced copy number, protein mislocalization, hemizygous deletion and promoter hypermethylation." (PMID 27825140, 2017). "To elucidate the role of RUNX3 in cancer cells, we transfected RUNX3 plasmids or vector control, RUNX3 siRNA or control siRNA into HepG2 and Hep3B cells." (PMID 28977878, 2017). "Recent evidence showed that RUNX3 inhibits ER signaling through suppressing the transcription activity of ERα and reducing ERα-dependent cancer cell proliferation." (PMID 27825140, 2017). "Whiles RUNX3 cannot notably suppress cancer cell proliferation; the N-t and RD constructs significantly suppress cell growth even in the TGF-β impaired context of AGS and MCF-7 cell lines." (PMID 29201108, 2017). "In B cells infected by the cancer-associated Epstein-Barr virus (EBV), RUNX3 and RUNX1 transcription is manipulated to control cell growth." (PMID 26883634, 2016). "RUNX3 showed protein silencing in cancer and normal mucosa, compared to inflammatory peritumoural infiltrate in almost all cases, showing a non-lymphocytic predominant pattern and being correlated with epigenetic silencing." (PMID 27566570, 2016). "Our study also opens new fields of investigation of the upregulation of tumor suppressor Runx3 in carcinoma cells or in other forms of acute lung injury and repair, in which lung epithelial cell apoptosis is generally a prominent feature." (PMID 26643317, 2015). "RUNX3 inactivation is a crucial factor to determine cancer pathogenesis and clinical outcome in a variety of cancer types." (PMID 25229459, 2014). "Because the EMT programme activation contributes to cancer cell invasion, we determined the invasive potential of cells transfected with control siRNA or RUNX3 siRNA." (PMID 24447545, 2014). "RUNX3 expression is also significantly lower in ER+ mammary ductal carcinomas (versus ER− cancers), suggesting that dysregulation of RUNX3 does play a role in the preference for ER+ breast tumorigenesis." (PMID 23704974, 2013). "Twenty-four hours after transfection, RUNX3 protein was significantly over-expressed in cancer cells." (PMID 23457532, 2013). "Transcriptional regulation of TSP-1 in osteogenesis and cancer is poorly understood; this prompted us to study its regulation by the two key regulators of the processes: Runx2 and Runx3." (PMID 23846726, 2013). "Subsequent studies demonstrated that the combination of hemizygous deletion of RUNX3 and the hypermethylation of RUNX3 promoter region contributes to the silencing of RUNX3 expression in various human cancers." (PMID 24078903, 2013). "The average number of complete tubular structures formed by HUVECs was significantly reduced in conditioned medium from RUNX3-overexpressing cancer cells compared with vector controls." (PMID 23457532, 2013). "The expression level of RUNX3 in human cancers is kept at extremely low level, and the higher RUNX3 expression level in human cancers is closely associated with a favorable prognosis with reduced recurrence and better survival rates in patients." (PMID 24078903, 2013). "By colocalization analysis we observed that CD8+ cells expressing RUNX3 decreased in carcinomas, while the presence of ThPOK increase in the same cells." (PMID 23349906, 2013).
cancer (continued). "RUNX3 (runt-related transcription factor-3) is a known tumor suppressor gene which exhibits potent antitumor activity in several carcinomas." (PMID 23457532, 2013). "In many cancer types, deletion of the RUNX3 locus and reduction of its expression by promoter hypermethylation has been reported." (PMID 21205319, 2011). "Previous studies have reported the involvement of RUNX3 promoter methylation in many cancers, including colorectal, gastric, bladder, breast, lung, oral, and nasopharyngeal cancers." (PMID 21867527, 2011). "In fact, RUNX3 frequency of RUNX3 positive cells is low in adult skin and oral mucosa, while most cancer cells expressed." (PMID 19521519, 2009). "When cancer tissue has grown from the tissue-specific stem cells, the cancer cells express the RUNX3 protein." (PMID 18475302, 2008). "Hypermethylation of the RUNX3 promoter and deletion of the RUNX3 gene are frequently observed in several cancers, and RUNX3 protein is now best considered as an apoptosis inducer." (PMID 18727821, 2008). "Induction of apoptosis by Tgf-β is well-documented in many cancer cell types; however, the role RunX3 plays in Tgf-β-dependent cell cycle arrest and apoptosis is unclear." (PMID 19412438, 2007). "RunX3 is a TSG which is frequently inactivated by allele loss or gene silencing due to promoter hypermethylation in GC and many other cancer types." (PMID 19412438, 2007). "RUNX3 expression can be clearly detected within the normal gastric epithelial cell layer, but only weakly in the cancer tissue." (PMID 15685235, 2005). "Moreover, an inverse correlation between EZH2 and RUNX3 expression has been shown to be dependent on the trimethylation of histone H3K27 on RUNX3 gene promoter, in several cancer cell lines." (PMID 39769907, 2024). "Although the ubiquitylation and degradation of RUNX3 has been reported in other cancer types, the role of MEX3C as the specific E3 ubiquitin ligase regulating this process in LUAD remains unknown." (PMID 38424632, 2024). "RUNX3 has been suggested as a potential therapeutic target for certain cancers, since restoration of RUNX3 expression by reactivation of Runx3 transcription or by overexpression, suppresses the proliferation of cancer cells." (PMID 36899853, 2023). "Because aberrant UPS activation is implicated in cancer development, establishing the interactions between ubiquitination and RUNX3 in cancer could further explain the ambivalent nature of RUNX3 in carcinogenesis." (PMID 36899853, 2023). "However, the role of RUNX3 in cancer is more nuanced and context-dependent, and there is emerging evidence of the oncogenic capacity of RUNX3 in various cancers." (PMID 36899853, 2023). "It is necessary to identify the SEs responsible for MYC upregulation by RUNX3, especially to determine whether depletion of these genomic elements suppresses tumorigenesis in animal cancer models." (PMID 37190031, 2023). "In contrast, Runx3 restoration recovers the oncogene surveillance mechanism and could, therefore, lead to inhibition of secondary oncogene activation as well as cancer regression." (PMID 37887282, 2023). "Interestingly, the most significantly upregulated genes in Ppm1dT/+ AML (Zbed3, Runx3, Marcks, Extl3, Pcbp4, Igf2bp3, Plch1, and Gdf6) were previously associated with AML and cancer progression." (PMID 37709843, 2023). "We therefore uncover a previously unknown mode of MYC destabilization by RUNX3 and provide an explanation as to why RUNX3 inhibits early-stage cancer development in gastrointestinal and lung mouse cancer models." (PMID 37400551, 2023). "For example, RUNX3 was shown to enhance tumorigenesis in acute myeloid leukemia, T-cell acute lymphoblastic lymphoma, natural killer/T-cell lymphoma, myelodysplastic syndrome, skin, head and neck, ovarian, and pancreatic cancers, and Ewing’s sarcoma." (PMID 37190031, 2023).